RAB19 (RAB19, member RAS oncogene family)
Description:
The small GTPases Rab are key regulators of intracellular membrane trafficking, from the formation of transport vesicles to their fusion with membranes. Rabs cycle between an inactive GDP-bound form and an active GTP-bound form that is able to recruit to membranes different set of downstream effectors directly responsible for vesicle formation, movement, tethering and fusion.
Synonyms: RAB19B
Tractability: Antibody: UniProt places it where antibodies can reach, with high confidence; its Gene Ontology location is reachable by antibodies, with medium confidence. PROTAC: ubiquitination databases record sites on it; its protein half-life has been measured.
Gene: Protein-coding gene on chromosome 7 (140,404,047 to 140,427,974, forward strand). Ensembl gene ENSG00000146955.
Subcellular location: Cell membrane
Pathways (Reactome):
Metabolism of proteins: RAB geranylgeranylation
Gene Ontology:
Molecular function: protein binding; GTPase activity; G protein activity; GTP binding
Biological process: autophagosome assembly
Cellular component: extracellular exosome; plasma membrane
Genetic constraint (gnomAD): Loss-of-function variants: 21 observed, 18.42 expected, observed/expected ratio (o/e) 1.14, 90% interval 0.81 to 1.63. The upper end of that interval is the gene's LOEUF score, 1.63, which puts it in group 6 of 6, group 1 being the genes least tolerant of losing a copy. Missense variants: 277 observed, 301.35 expected, observed/expected ratio (o/e) 0.92, 90% interval 0.83 to 1.01. Synonymous variants: 126 observed, 116.34 expected, observed/expected ratio (o/e) 1.08, 90% interval 0.94 to 1.26.
Homologues: Orthologues: chimpanzee RAB19 (100% identical), macaque RAB19 (97% identical), pig RAB19 (90% identical), rat Rab19 (90% identical), dog RAB19 (89% identical), mouse Rab19 (89% identical), rabbit RAB19 (89% identical), guinea pig RAB19 (84% identical), tropical clawed frog rab19 (71% identical), zebrafish RAB19 (63% identical), zebrafish RAB19 (39% identical). Paralogues in human: RAB43 (52% identical), RAB30 (45% identical), RAB1A (41% identical), RAB1B (40% identical), RAB8B (40% identical), RAB11B (39% identical), RAB13 (39% identical), RAB2B (39% identical), RAB11A (39% identical), RAB37 (38% identical), RAB26 (38% identical), RAB10 (37% identical), and 56 more.
Diseases named in the same sentence as RAB19 in open-access papers:
RAB19 is named in the same sentence as 14 diseases in open-access papers, as found by Europe PMC text mining. Sharing a sentence is not in itself a finding about the gene and the disease. The quoted sentences say what the papers report.
gastric cancer (4 papers, 2021 to 2023). A primary or metastatic malignant neoplasm involving the stomach. "The m6A-mediated upregulation of LINC01320 promotes the proliferation, migration, and invasion of gastric cancer via the miR495-5p/RAB19 axis." (PMID 35778697, 2022). "Mechanistically, METTL14-mediated m6A modification induces the up-regulation of LINC01320, which subsequently affects gastric cancer progression through the miR-495-5p/RAB19 axis." (PMID 34288797, 2021). "Overexpressed LINC01320 contributed to the aggressive phenotype of gastric cancer cells via regulating the miR-495-5p/RAB19 axis." (PMID 34288797, 2021). "Additionally, LINC01320-induced increases in cell viability, migration, and invasion of gastric cancer were alleviated by miR-495-5p and silenced RAB19." (PMID 34288797, 2021). "This study found that RAB19 was significantly up-regulated in gastric cancer, suggesting that it may function as an oncogene in gastric cancer." (PMID 34288797, 2021). "Moreover, down-regulation of RAB19 antagonized the aggressive behaviors of gastric cancer induced by LINC01320 overexpression." (PMID 34288797, 2021). "Hence, the METTL14/LINC01320/miR-495-5p/RAB19 axis may play a positive role in the development of gastric cancer." (PMID 34288797, 2021). "In gastric cancer, METTL14-mediated m6A modification led to LINC01320 upregulation, which promoted an aggressive phenotype of increased cancer cell proliferation, migration, and invasion via regulating the miR-495-5p/RAB19 axis." (PMID 37029420, 2023). "The effect of the LINC01320/miR-495-5p/RAB19 axis on gastric cancer has not been studied at the animal level." (PMID 34288797, 2021). "However, the roles of RAB19 in gastric cancer have not been elucidated." (PMID 34288797, 2021).
ciliopathies (1 paper, 2024). "Thus, the indirect role of lysosomal trafficking in regulating Rab19 activity for ciliogenesis is potentially relevant to a variety of diseases ranging from ciliopathies to malaria." (PMID 37665101, 2024).
gastric adenocarcinoma (1 paper, 2022). "What’s more, in vitro, interference of RAB19 was shown to promote invasion and migration of gastric adenocarcinoma cells, while its overexpression inhibited these functions, suggesting a potential therapeutic role for RAB19 in stomach adenocarcinoma." (PMID 35859893, 2022).
oral squamous cell carcinoma (1 paper, 2021). "It was reported that RAB19 is negatively correlated with the tumor purity of oral squamous cell carcinoma and positively correlated with the immune infiltration of B cells, CD8 + T cells, CD4 + T cells, macrophages, neutrophils, and dendritic cells." (PMID 34288797, 2021).
infection (1 paper, 2020). The state of being infected such as from the introduction of a foreign agent such as serum, vaccine, antigenic substance or organism. "Several other Rabs displaying close phylogenetic relationship to Rab1, including Rab8, Rab18, Rab35, Rab33, Rab30, Rab19, and Rab37, could also be modified by SseK3 upon infection." (PMID 32504010, 2020).
neurological disorders (1 paper, 2024). "Investigating whether Rab19 is mislocalized and whether ciliogenesis is impaired by these HOPS mutations could inform potential treatments for HOPS-associated neurological disorders." (PMID 37665101, 2024).
RAB19 also shares sentences with these, for which no sentence is quoted: tumor (2 papers); adenocarcinoma (1); cancer (1); colorectal cancer (1); Joubert syndrome (1); malaria (1); polycystic kidney disease (1); Stomach (1).